EXT1 (exostosin glycosyltransferase 1)
Diseases named in the same sentence as EXT1 in open-access papers (continued):
Sharing a sentence is not in itself a finding about the gene and the disease.
osteoporosis (1 paper, 2022). A condition of reduced bone mass, with decreased cortical thickness and a decrease in the number and size of the trabeculae of cancellous bone (but normal chemical composition), resulting in increased fracture incidence. "The main conclusion of our study is that all three extracts, especially RED EXT1 from red cornelian cherry fruits, possess the antiosteoporotic potential and may be a promising phytomedicine candidate for the prevention and treatment of osteoporosis." (PMID 36225173, 2022).
ovarian carcinoma (1 paper, 2023). A malignant neoplasm originating from the surface ovarian epithelium. "Previous studies showed direct evidence that loss-of-function of KLF6 or HNF1B decreased expression of EXT1 in cultured mouse bone marrow-derived macrophages or ovarian cancer cell line SKOV3." (PMID 37308486, 2023).
Ovarian cyst (1 paper, 2010). The presence of one or more cysts of the ovary. "Interestingly, patients affected with both LEMD3 and EXT1 mutations presented spectrum of additional non-skeletal pathologies, which included: (IV:15) TOF and ovarian cysts, (IV:17) sinus cysts, and (III:13) diabetes melitus type 2 and vitiligo." (PMID 20618940, 2010).
pancreatic cancers (1 paper, 2023). "In human colon and pancreatic cancers, we carefully evaluated EXT1 expression only in fibroblasts in the TME." (PMID 36809261, 2023).
papillary thyroid carcinoma (1 paper, 2025). "One case of papillary thyroid carcinoma was described in a 36-year-old man from the Netherlands; no EXT1 or EXT2 mutations were identified." (PMID 41441317, 2025).
Pick disease (1 paper, 2015). A rare neurodegenerative disorder leading to dementia. "Cathepsin L (CTSL), which primes the filovirus glycoprotein in the endosome, EXT1, which is involved in biosynthesis of heparan sulfate, and Niemann-Pick disease, type C1 (NPC1), showed strong bias against MARV entry." (PMID 26596270, 2015).
schizophrenia (1 paper, 2017). A major psychotic disorder characterized by abnormalities in the perception or expression of reality. "In addition to novel GWS loci, we have identified a significant genetic correlation with schizophrenia and association of ASD with several neurodevelopmental-related genes such as EXT1, ASTN2, MACROD2, and HDAC4." (PMID 28540026, 2017).
tongue cancer (1 paper, 2019). A malignant neoplasm affecting the tongue. "Assessment of ECS, an additional prognosticator in advanced stage disease, indicated a distinct set of markers in tongue cancer (EXT1, GMPS, TSTA3), while in laryngopharyngeal cancers a majority of the markers were common those associated with late stage disease." (PMID 31310629, 2019).
tumor (51 papers, 2008 to 2026). "Similar to DAPK3, EXT1 is commonly associated with hypermethylated CpG islands, reduced heparan sulfate production, and tumor suppressor‐like functions in various cancers." (PMID 39254643, 2024). "The expression of EXT1 was significantly associated with gender, and the methylation status of cg03276982 was correlated with age and primary tumour stage." (PMID 33565239, 2021). "Concurrently, overexpression of EXT1 was found to cause more tumor burden than control Jurkat T-ALL cells, demonstrating a dosage lethality effect of EXT1 in the Jurkat T cell model." (PMID 33962942, 2021). "Previous studies on the genetic linkage for this disease reported some loci on the chromosomes, with mutation analyses identifying two genes as tumor suppressors: exostosin 1 (EXT1) and exostosin 2 (EXT2)." (PMID 32843889, 2020). "Consistent with in vitro studies, there was a significant reduction in tumor volume in mice that had received EXT1 deficient HCC cells compared with animals that received control Hep3B and Huh7 cells (−vector)." (PMID 31200735, 2019). "Epigenetic silencing of EXT1 by hypermethylation in the promoter region results in loss of HS synthesis and promotes tumor progression in cancer cells, which can be reversed by a DNA demethylating agent." (PMID 28672878, 2017). "In almost 90% of MO patients germline mutations in the tumour suppressor genes EXT1 or EXT2 are found." (PMID 18271966, 2008). "Because EXT1 encodes a key HS polymerase, its enrichment in vascular territories supports the hypothesis that it contributes to angiogenesis and endothelial-tumor communication." (PMID 41438585, 2026). "Additionally, the relationship between cell surface HS reduction, related to Ext1 gene mutations, and fibroblasts has been reported using a spheroid tumor cell/fibroblast co-culture model." (PMID 36809261, 2023). "EXT1 (cg02905663), a regulator of apoptosis and heparan sulfate biosynthesis, functions as a tumor suppressor in ALL through ERK1/2 signaling modulation and interacts with NOTCH1-FBXW7 pathways." (PMID 40730747, 2025). "This disorder is associated with loss-of-function mutations in the EXT1 and EXT2 genes, which are considered tumor-suppressor genes." (PMID 40390716, 2025). "Since this pathology is triggered by genetic mutations and dysfunction of EXT1 and EXT2, both were considered as potential tumor suppressors." (PMID 36982528, 2023). "Additional Fc1(a) solo-LTR insertions within genes include, but are not limited to, homologs involved in tumor suppression (EXT1) and immune functions (WDFY4)." (PMID 38055724, 2023). "This implies that knockdown of EXT1, considered as a tumor suppressor in earlier studies, has additional consequences beyond the synthesis of HS." (PMID 36982528, 2023). "We performed immunofluorescence staining to examine Ext1 and vimentin expression of Tomato-positive cells of Pan02 tumor tissue in S100a4-Cre; Ext1f/f; Lsl-tdTomato and control mice." (PMID 36809261, 2023). "Although our present findings highlight EXT1 as a tumor suppressor, shifting cellular HSPG formation indirectly into an anti-tumorigenic context, several aspects remain open and give reason for future studies." (PMID 36982528, 2023). "In contrast, the tumor-suppressor function of EXT1 has been reported in sporadic human malignancies." (PMID 37308486, 2023). "Nevertheless, the fact that EXT1 is epigenetically downregulated in numerous cancer cells supports its estimation as a tumor suppressor." (PMID 36982528, 2023). "EXT1 and EXT2 are tumor suppressor genes that encode glycosyltransferases involved in the biosynthesis of heparan sulfate." (PMID 35955863, 2022). "Both genes that encode exostosin glycosyltransferases (EXT1 and EXT2) function as tumor‐suppressors, although the molecular mechanisms and prognostic value of exostosins (EXTs) in cancer is still unclear." (PMID 33314711, 2021).
tumor (continued). "Germline heterozygous loss-of-function mutations in the EXT1 (exostosin-1, located on chromosome 8q23-q24) or EXT2 (exostosin-2, located on chromosome 11p11-p12) tumor suppressor genes are responsible for over 70–95% of HME cases." (PMID 33632255, 2021). "Pearson Correlation Analysis of gene expression among the 21 tumor samples revealed that EXT1 showed strong correlation to all the other enzymes (r > 0.8 for EXT2, NDST1, and HS6ST1)." (PMID 33585200, 2020). "Further exploration of gene expression in FFPE tumor sections from HNSCC patients revealed that EXT1 is significantly elevated in SULF2-positive tumor tissues." (PMID 33585200, 2020). "EXT1, with documented tumour suppressor properties, is involved in the initiation and polymerisation of the growing HS chain." (PMID 32398079, 2020). "Immunohistochemistry (IHC) analysis of tumor biopsy samples confirmed a loss of CSMD2 and enhanced EXT1 expression in tumor and PVTT cells, whereas MED30 expression was unchanged (data not shown)." (PMID 31200735, 2019). "In the current study, we for the first time show EXT1 levels are elevated in human HCC samples compared to the adjacent non-tumor." (PMID 31200735, 2019). "We validated EXT1 as a tumor promoter with an siRNA-mediated approach in MCF7/ADR cells, and revealed its novel role as a regulator of CSC properties." (PMID 29050299, 2017). "In Grade II-III tumours, there was a 4-fold decrease in the EXT1 expression level, though the EXT2 expression was maintained, whereas in GBM tissues (Grade IV) the EXT2 expression level was decreased by 3–4-fold as well (p < 0.05)." (PMID 29104277, 2017). "Introduction of a functional EXT1 gene into cancer cell lines induces tumor-suppressor-like features, such as reduced colony formation and tumor growth in nude mouse xenografts." (PMID 28261562, 2017). "EXT1 expression was reported to be epigenetically silenced in tumors, while the restoration of EXT1 expression in cancer cells induced tumor-suppressive effects." (PMID 23457527, 2013). "In mice administered adenoviruses expressing either TGFBR2 or EXT1, tumor growth suppression by IFN-α/5-FU was significantly enhanced compared with that in controls." (PMID 23457527, 2013). "This is the first demonstration that stromal Ext1-levels modulate tumor cell proliferation and affect the interstitial fluid pressure in a 3-D spheroid model." (PMID 22848466, 2012). "Additionally, EXT1 was modestly upregulated in recurrent compared to primary tumors and showed a positive correlation with tumor progression metrics." (PMID 41438585, 2026). "Both genes (EXT1 and EXT2) encoding exocrine glycosyltransferases have tumor-suppressive functions, although the details of mechanisms and predictions of the prognostic value of exostosin in cancer remain unclear." (PMID 38293671, 2023). "However, although these aspects support the idea that EXT1 acts as a tumor suppressor, other studies detected a supporting role of EXT1 in tumor growth and malignancy." (PMID 36982528, 2023). "The epigenetic gene silencing of EXT1 by CpG island promoter hypermethylation appears as a common issue in multiple leukemic and non-melanomic skin cancer cells, associated with reduced HSPG formation and increased tumor cell proliferation." (PMID 36982528, 2023). "Hence, to investigate how fibroblast HS affects the tumor stromal environment in vivo, we generated fibroblast-specific Ext1 conditional knockout mice by crossing Ext1flox/flox with S100a4-Cre/+ mice." (PMID 36809261, 2023). "And EXT1 may affect tumor survival by activating the Wnt signaling pathway By PPI network analysis, we found that EXT1 was associated with KIF2C." (PMID 35685442, 2022). "Moreover EXT1‐dependent HS structure is involved in modifying tumor‐stroma interactions through altering stromal TGF‐ß1 expression in human A549 carcinoma cells." (PMID 33314711, 2021).
tumor (continued). "This supports the hypothesis that genetic factors other than EXT1 or EXT2 mutations, such as CDKN2A, are involved in tumor progression." (PMID 32295254, 2020). "Furthermore, in vitro tumorigenicity assays showed that shRNA knockdown of EXT1 significantly decreased tumor growth of Hep3B and Huh7 cells, compared with cells treated with a scrambled shRNA control." (PMID 31200735, 2019). "Furthermore, overexpressing EXT1 in HCC induces the tumor proliferation whereas knockdown EXT1 reduced tumor growth in vitro and in vivo." (PMID 31200735, 2019). "The fact that EXT1 levels rose as early as 1 month before tumor development, and that it was also found to be elevated in the plasma of human patients with CCA, indicate that it might be useful as an early diagnostic biomarker of the disease." (PMID 28672878, 2017). "Furthermore, TGFBR2 and EXT1 overexpression enhanced the anti-tumor effects of IFN-α/5-FU on HCC cells." (PMID 23457527, 2013). "In addition, using fibroblasts with a mutation in Ext1, we herein demonstrate a central role of stromal HSPG for spheroid formation, the Pif and tumor cell migration within these spheroids." (PMID 22848466, 2012). "The molecular mechanism by which stromal Ext1 levels, and the resulting changes in HS chain length modulate tumor cell migration and Pif was beyond the scope of this study but may involve, ECM assembly, growth factor signaling and/or MMPs." (PMID 22848466, 2012). "We performed immunofluorescence staining to examine Ext1 and vimentin expression of Tomato-positive cells of MC38 tumor tissue in S100a4-Cre; Ext1f/f; Lsl-tdTomato and control mice." (PMID 36809261, 2023). "All four genes (EXTL2, EXTL3, EXT1, and EXT2) involved in elongation of the backbone of HS chains are significantly >2-fold upregulated in tumor compared to the adjacent benign tissues." (PMID 33585200, 2020). "Surprisingly, we also found that there were partial losses of certain oncogenes (FGFR1, PDGFRA, and so on) and amplifications of certain tumor suppressors (NBN, EXT1, and so on) in these cell lines." (PMID 29880898, 2018). "Comparison of gene expression in Set 1 with the Sanger COSMIC dataset identified five down-regulated genes that have previously been confirmed to result in neoplasia; these included CEBPA, ERBB2, EXT1, PIM1, and SDHD." (PMID 25023465, 2014). "For the HBV integration hotspot at chr8, EXT1 showed significantly higher expression in tumor tissue than in adjacent non-neoplastic liver tissues." (PMID 35710421, 2022). "EXT1, EXT2, and SULF2 are probably co-upregulated in tumor tissues according to the correlation analysis and higher gene expression in SULF2-positive tumors than in SULF2-negative tumors, but the mechanism underlying such upregulation still needs to be further explored." (PMID 33585200, 2020). "Several other genes synthesizing the HS chains are upregulated in tumor tissues, and groups of the genes (e.g. EXT1, EXT2, and SULF2) may be jointly regulated in the tumor tissues." (PMID 33585200, 2020). "The Ext1-dependend influence on the Pif was not restricted to a single tumor cell line or spheroid growth condition, as similar difference in central Pif was observed also for H460 containing composite spheroids grown as hanging drops." (PMID 22848466, 2012). "It is not something unexpected - tumour-suppressor function was shown for another HS-synthesizing enzyme EXT1, which is responsible for the initial step of heparan sulfate (HS) chain elongation." (PMID 20723247, 2010). "Furthermore, the absence of genetic testing for EXT1/EXT2 mutations and inflammatory marker analysis limits a more detailed understanding of the tumor’s pathogenesis." (PMID 41181450, 2025). "Tumor-cell-induced platelet activation (TCIPA) strictly depends on thrombin formation, raising the question whether thrombin, accelerated in formation by the increased TF activity of EXT1 kd cells, also contributes to tumor cell resistance in MV3EXT1kd cells." (PMID 36982528, 2023).
cancer (41 papers, 2010 to 2026). A tumor composed of atypical neoplastic, often pleomorphic cells that invade other tissues. "Further analysis of the expression of Ext1 and Ext2 in cancer cells and fibroblasts is needed to gain a better understanding of how TME with Ext1 loss of fibroblasts can lead to cancer development." (PMID 36809261, 2023). "In a systematic interactome study, we previously showed that EXT1, an ER-resident type II transmembrane glycosyltransferase, interacts with Notch1, a type I transmembrane receptor that is frequently mutated in cancers." (PMID 33962942, 2021). "Multiple pieces of evidence indicate that EXT1 is broadly implicated in cancer, as suggested by the findings shared in the Cancer Cell Line Encyclopedia, TCGA, and Catalogue of Somatic Mutations in Cancer." (PMID 33962942, 2021). "How EXT1 loss leads to cancer is poorly understood (Bovée, 2008); nonetheless, eight other known aminoglycan synthesis genes participate in the same gene community." (PMID 30573688, 2018). "Future studies will be ensured to address the underlying mechanisms and also determine whether EXT1 level in HCC tissues could serve as a prognostic marker for cancer therapy." (PMID 31200735, 2019). "EXT1 represents a clinically relevant biomarker and a promising therapeutic target in inflammation-driven cancers like PAAD and LUAD." (PMID 42232599, 2026). "These approaches identified several oncogenes, including KRAS, CREBBP, PTEN, and BRCA2, as SDL genetic partners of EXT1, highlighting its potential clinical relevance in different cancers." (PMID 33962942, 2021). "While investigating the role of EXT1 in thymocyte development and cancer, we found that reduction of the EXT1 protein results in global changes in cellular homeostasis, including cell size, organelle shapes and interactions, and cellular metabolism." (PMID 33962942, 2021). "In this study, we investigated the role of exostoxin 1 (EXT1), an endoplasmic reticulum (ER)-residing type II transmembrane glycoprotein, in cancer cell stemness." (PMID 29050299, 2017). "Among the most highly upregulated genes, we selected EXT1 for further analysis, as EXT1 gene has been previously reported to have a potential role in cancer progression." (PMID 29050299, 2017). "EXT1 (Exostosin-1), a glycosyltransferase, is another highly upregulated gene whose expression is reduced in human cancer cells by DNA methylation." (PMID 28261562, 2017). "siRNA-mediated knockdown of EXT1 in MCF7/ADR cells significantly reduced cancer stem cell markers, populations of ALDH+and CD44+/CD24- cells, mRNA and protein expression for CD44, and mammosphere number." (PMID 29050299, 2017). "Collectively, we demonstrated the critical role of enhanced EXT1 in regulating cancer cell stemness in doxo-resistant MCF7/ADR cells." (PMID 29050299, 2017). "Furthermore, we performed double immunofluorescence of Ext1 and vimentin on human cancer stroma, and we confirmed that Ext1-positive fibroblasts were vimentin-positive." (PMID 36809261, 2023). "In addition, EXT1 was demonstrated to participate in the process of cancer proliferation and migration by methylation regulation." (PMID 37091782, 2023). "Furthermore, individual variability in the expression levels of EXT1 was observed in the CAFs of human cancer specimens." (PMID 36809261, 2023). "Further research is warranted to evaluate targeting EXT1 in these types of cancers." (PMID 35710421, 2022). "Notably, the difference in expression levels between cancer and adjacent normal tissues was statistically significant only for of EXT1 in the Talbot Lung and Hou Lung datasets." (PMID 33314711, 2021). "To further demonstrate a potential global role of EXT1 in cancer, we took advantage of the SL and the SDL principles, whereby, for each pair, individual gene inactivation (SL) or expression variation (SDL) result in viable phenotypes, whereas combined perturbations are lethal." (PMID 33962942, 2021).